ID2 (inhibitor of DNA binding 2)
Description:
Transcriptional regulator (lacking a basic DNA binding domain) which negatively regulates the basic helix-loop-helix (bHLH) transcription factors by forming heterodimers and inhibiting their DNA binding and transcriptional activity. Implicated in regulating a variety of cellular processes, including cellular growth, senescence, differentiation, apoptosis, angiogenesis, and neoplastic transformation. Inhibits skeletal muscle and cardiac myocyte differentiation. Regulates the circadian clock by repressing the transcriptional activator activity of the CLOCK-BMAL1 heterodimer. Restricts the CLOCK and BMAL1 localization to the cytoplasm. Plays a role in both the input and output pathways of the circadian clock: in the input component, is involved in modulating the magnitude of photic entrainment and in the output component, contributes to the regulation of a variety of liver clock-controlled genes involved in lipid metabolism.
Synonyms: bHLHb26; GIG8; ID2A; ID2H
Tractability: PROTAC: UniProt records ubiquitination sites on it; ubiquitination databases record sites on it.
Gene: Protein-coding gene on chromosome 2 (8,678,845 to 8,684,461, forward strand). Ensembl gene ENSG00000115738.
Subcellular location: Cytoplasm; Nucleus
Subcellular location (Human Protein Atlas): Nuclear bodies; Nucleoplasm; Centrosome
Pathways (Reactome):
Signal Transduction: NGF-stimulated transcription
Gene Ontology:
Molecular function: protein binding; transmembrane transporter binding; RNA polymerase II-specific DNA-binding transcription factor binding; transcription corepressor activity; transcription regulator inhibitor activity; protein dimerization activity
Biological process: negative regulation of DNA-templated transcription; regulation of G1/S transition of mitotic cell cycle; regulation of transcription by RNA polymerase II; bundle of His development; cellular senescence; circadian regulation of gene expression; circadian rhythm; embryonic digestive tract morphogenesis; endodermal digestive tract morphogenesis; entrainment of circadian clock by photoperiod; enucleate erythrocyte differentiation; epithelial cell differentiation involved in mammary gland alveolus development; heart development; locomotor rhythm; mammary gland alveolus development; mammary gland epithelial cell proliferation; negative regulation of B cell differentiation; negative regulation of gene expression; negative regulation of muscle cell differentiation; negative regulation of transcription by RNA polymerase II; neuron differentiation; neuron fate commitment; olfactory bulb development; positive regulation of astrocyte differentiation; positive regulation of blood pressure; and 10 more
Cellular component: cytoplasm; cytosol; nucleus; euchromatin; nucleoplasm; protein-containing complex
Genetic constraint (gnomAD): Loss-of-function variants: 2 observed, 8.31 expected, observed/expected ratio (o/e) 0.24, 90% interval 0.097 to 0.76. That is too few expected variants to judge how well the gene tolerates losing a copy. Missense variants: 155 observed, 175.58 expected, observed/expected ratio (o/e) 0.88, 90% interval 0.77 to 1.01. Synonymous variants: 112 observed, 77.78 expected, observed/expected ratio (o/e) 1.44, 90% interval 1.24 to 1.68.
Gene-disease validity (ClinGen):
ClinGen rates the evidence that ID2 causes each of these diseases.
congenital heart disease (autosomal dominant): Disputed. A heart disease that is present at birth.
Homologues: Orthologues: chimpanzee ID2 (100% identical), macaque ID2 (100% identical), dog ID2 (99% identical), mouse Id2 (99% identical), pig ID2 (99% identical), guinea pig ID2 (97% identical), rat Id2 (90% identical), zebrafish id2a (80% identical), tropical clawed frog id2 (62% identical), zebrafish id2b (58% identical), rabbit ID2 (57% identical), Drosophila melanogaster emc (40% identical). Paralogues in human: ID4 (50% identical), ID1 (47% identical), ID3 (41% identical).
Diseases named in the same sentence as ID2 in open-access papers:
ID2 is named in the same sentence as 188 diseases in open-access papers, as found by Europe PMC text mining. Sharing a sentence is not in itself a finding about the gene and the disease. The quoted sentences say what the papers report.
breast cancer (34 papers, 2004 to 2025). A primary or metastatic malignant neoplasm involving the breast. "In short, our data demonstrate that E-cadherin loss causes Id2 upregulation in breast cancer cells under anchorage independent conditions." (PMID 35437308, 2022). "Next, we analyzed if E-cadherin is causal to the regulation of Id2 expression in ER positive human breast cancer cells." (PMID 35437308, 2022). "Chromatin immunoprecipitation (ChIP) assays using monoclonal Kaiso antibodies combined with an Id2-specific PCR confirms that Id2 is a Kaiso target gene in mouse and human E-cadherin deficient breast cancer cells (mILC-1 and MDA-MB231)." (PMID 35437308, 2022). "In short, anchorage independent Id2 mRNA upregulation is causally linked to E-cadherin expression in PDO breast cancer models." (PMID 35437308, 2022). "For instance, it was shown that a higher expression level of ID2 (i.e., the target gene of enhancer chr2:8440002–8455200) was associated with advanced breast cancer." (PMID 34879086, 2021). "It has been reported that the upregulation of ID2 in breast cancer is associated with a reduced vimentin expression and attenuated EMT features in triple-negative breast carcinomas." (PMID 35008299, 2021). "For example, inhibitor of DNA binding 2 (ID2) is downregulated in breast cancer, in which it inhibits cellular invasion and associated with favorable prognostic factor for patients." (PMID 33247706, 2020). "ID2 promotes differentiation of breast epithelial cells and its reduced expression in breast cancer is associated with an unfavorable prognosis." (PMID 24980816, 2014). "These in vivo assays demonstrate that Id2 knockdown fully prevents lung colonization compared to controls (0/6 versus 7/8 mice, p < 0.0001), indicating that Id2 is required for metastatic colonization of E-cadherin deficient breast cancer cells." (PMID 35437308, 2022). "Also, Id2 expression has been implicated in the maintenance of breast cancer stemness and possible control over the transition from ductal carcinoma in situ (DCIS) to invasive cancer." (PMID 35437308, 2022). "Moreover, elevated ID2 expression identifies breast cancer patients at increased risk of developing metastatic relapse in the brain." (PMID 30642388, 2019). "Moreover, in ER– breast cancers, elevated expression of either ID2 or ALDH3A1 was associated with reduced distant metastasis-free survival." (PMID 30642388, 2019). "Several of the other predictions are for proteins that have a known role in both DNA damage, NPAS2 and ID2, and breast cancer." (PMID 40646689, 2025). "For instance, in breast cancer patients, monocytes showed reduced expression of inhibitor of DNA binding 2 (ID2), which is vital for DC differentiation." (PMID 38351552, 2024). "The analysis further revealed that MCU, alongside genes commonly mutated in breast cancer, demonstrated elevated expression levels comparable to key T cell regulators such as AHR, ID2, and TBFb1." (PMID 38632642, 2024). "Functionally, Id2 promotes a low proliferative indolent state in lobular breast cancer cells through inhibition of CDK4/6-Rb-dependent cell cycle progression, enabling anchorage independence and subsequent metastatic dissemination." (PMID 35437308, 2022). "Increased Id2 levels in breast cancer correlate to poor prognosis, and a recent report has identified Id2 as a promoter of breast cancer colonization to the brain." (PMID 35437308, 2022). "Aberrant expression levels of ID2 protein have been reported in a variety of cancers, such as non-small cell lung cancer, breast cancer, esophageal squamous cell carcinoma (ESCC), and colorectal cancer." (PMID 34746132, 2021). "The member ID2 has been reported as a prognostic marker in breast cancer patients, as well as a key regulator of breast cancer metastasis to the brain." (PMID 34490085, 2021).
breast cancer (continued). "Our data support a model in which breast cancer cells that have disseminated to the brain upregulate ID2 expression in response to astrocyte-secreted BMP7 and this serves to support metastatic expansion." (PMID 30642388, 2019). "For example, inhibitor of DNA binding 2 (ID2) is downregulated in breast cancer, in which it inhibits cellular invasion and is a favorable prognostic factor for patients." (PMID 29089860, 2017). "We excluded an exclusive relationship between Dies1 and BMP-signalling in the breast cancer model by assessing the expression of ID2/ID3, as these genes were systematically downregulated independently of Dies1 expression." (PMID 27721458, 2016). "ID2 is pro-proliferative and pro-metastatic in neuroblastoma cells, whereas it helps in the maintenance of a non-invasive phenotype in breast cancer cells." (PMID 22848373, 2012). "Elevated levels of Id2 expression have been reported in carcinomas of breast, ovary, colon and prostate, in neural tumors, melanoma, Ewing's sarcoma and in hematological malignancies." (PMID 19257909, 2009). "Some new substrates of USP1 have also been found in several tumors, such as karyopherin subunit alpha 2 and ERa in breast cancer, ID2 in gastric cancer, c-kit and TBLR1 in liver cancer, TAZ in osteosarcoma and hepatocellular carcinoma, Snail in ovarian cancer, and PARP1 in cholangiocarcinoma." (PMID 39513905, 2024). "Finally, we find that Id2 is indeed enriched in ILC when compared to other breast cancers, and confirm cytosolic Id2 protein expression in primary ILC samples." (PMID 35437308, 2022). "The development of reagents that can inhibit ID2 dimerisation or promote its degradation will, in the future, allow robust assessment of ID2 as a potential therapeutic target to prevent or limit the development of breast cancer brain metastasis." (PMID 30642388, 2019). "This study identifies ID2 as a key regulator of breast cancer metastasis to the brain." (PMID 30642388, 2019). "In the breast cancer cell line MDA-MB-231, the genes ID2 and ID3 have been demonstrated to be under the control of P-TEFb, and reduced P-TEFb recruitment/activity has been suggested to underlie downregulated expression of ID2 and ID3 upon MEPCE depletion." (PMID 31467394, 2019). "Similarly, Foxf2 is essential for the proper downregulation of E-cadherin and the regulation of Zeb2 and Id2 during a TGFβ-induced EMT of Py2T murine breast cancer cells that have been derived from a tumor of the MMTV-PyMT mouse model of breast cancer." (PMID 30285803, 2018). "High level of Id-2 has been demonstrated to reduce breast cancer cells invasiveness and therefore could act as a favourable prognostic marker for breast cancer patients." (PMID 18000500, 2007). "In addition, high level of Id-2 expression has been shown to reduce the invasiveness of breast cancer cells and can act clinically as a favourable prognostic marker." (PMID 18000500, 2007). "Together, these results establish Id2 as a novel and p120-responsive transcriptional Kaiso target on its canonical target site and provide a mechanistic rationale for the Id2-dependent pro-metastatic control over anoikis resistance in E-cadherin mutant breast cancer cells." (PMID 35437308, 2022). "Indeed, downstream of SMAD proteins, HMGA2 was resolved to directly activate zinc-finger transcription families Snail, Slug, and Twist and downregulate Inhibitor of differentiation 2 (Id2) in mammary tumor cells which altogether are known to repress E-cadherin (CDH1) expression." (PMID 32365712, 2020). "Moreover, whereas treatment with TGFβ1 had little impact on ID2 expression in either mouse mammary carcinoma or human breast cancer cells, BMP7 treatment resulted in a > 50-fold increase in ID2 mRNA levels and this level of expression was sustained for at least 5 days following BMP7 withdrawal." (PMID 30642388, 2019).
breast cancer (continued). "In addition, ID2 can be induced by HIF-1 and HIF-2 (Hypoxia induced factors), which might contribute to ID2 expression in breast cancer cells." (PMID 20070914, 2010). "However, action of ID2 could also be tissue specific: in breast cancer cell lines, high expression of ID2 reduced growth potential and invasiveness, while up-regulation of ID2 increased proliferation and invasive potential in prostate tumor cells." (PMID 19129913, 2009). "Thus, ID4 may have the opposite function of ID1 and ID2, which are thought to have oncogenic properties in human breast cancer cells." (PMID 18513385, 2008). "By showing that forced expression of Wnt1 in the mammary gland is capable of overcoming the block to proliferation caused by the absence of Id2, we conclude that functional Id2 expression is not required for Wnt1 to induce mammary hyperplasia and mammary tumors." (PMID 15601467, 2004). "We propose that inactivation of E-cadherin, a lobular histology, and cytosolic Id2, should be considered as criteria to include ERNEG and HER2POS ILC patients for clinical CDK4/6 breast cancer intervention trials." (PMID 35437308, 2022). "Using a clinical breast cancer tissue microarray (TMA), we analyzed subcellular distribution of Id2 in 148 invasive breast cancers and observe that ILC cases more often display cytosolic Id2 localization compared to IDC-NST (p = 0.0004)." (PMID 35437308, 2022). "CBD has also been shown to downregulate Id-1 in the aggressive human breast cancer line MDA-MB-231 through modulation of ERK and ROS pathways leading to a decrease in Id-1 expression and also upregulated Id-2 (a transcriptional regulator)." (PMID 34259916, 2021). "The regulatory network TRIM24 was involved in showed that TRIM24, YAP1, Ifn, Ifnar, SOCS1, and S100A8 together activated atherogenesis and cell viability of breast cancer cell lines through 18 genes, including AKT1, ID2, etc.." (PMID 34575874, 2021). "Examination of the TCGA breast cancer dataset revealed higher levels of ID2 and ALDH3A1 expression in triple-negative (ER–/PR–/HER2–) breast cancers compared with HER2+ and ER+/HER2– breast cancers, and in ER– versus ER+ breast cancers." (PMID 30642388, 2019). "For instance, in breast cancer, another independent study reported both ID1 and ID2 overexpression were related to the advanced tumor stage, shorter OS and disease free survival." (PMID 29190891, 2017). "The possibility exists that phospho-ablated Id2 interacts with the death domain cascade, as caspase 8 has been shown to activate caspase 3 in MDA-MB231 breast cancer cells treated with etoposide." (PMID 19609365, 2009). "Although a high expression of Id2 in primary breast cancer cells was reported to confer favorable clinical outcome, our findings suggest that the analysis of Id2 expression in combination with ERα status may be better for prognostic reevaluation of breast cancer." (PMID 19257909, 2009). "In line with our findings in breast cancer cell lines, we observe a 4-fold increase of Id2 mRNA levels in the E-cadherin negative KCL320 upon transfer to anchorage-independence, but not in the E-cadherin expressing ILC PDO P008." (PMID 35437308, 2022). "In addition, transcription factors known as tumor suppressors or genes related to breast cancer including c-FOS, EGR1, ID2 and SERPINB2, as well as suppression of metastasis associated genes (CD44 and IL11) have emerged as molecular targets of BSP knockdown." (PMID 24980816, 2014). "Furthermore, we detected upregulation of genes that are downregulated in the primaries of breast cancer patients, including c-FOS, EGR1 and ID2." (PMID 24980816, 2014). "In breast cancer, Id-2 expressed at high levels maintains the cancer cells in a non-aggressive phenotype." (PMID 18000500, 2007). "We conclude that functional Id2 expression is not required for Wnt1 to induce mammary hyperplasia and mammary tumors." (PMID 15601467, 2004).
breast cancer (continued). "Others have also observed an inverse correlation in ID1 and ID2 expression in patients’ chronic myelogenous leukemia (CML) and blast crisis cells and in nonhematopoietic tissue, where loss of ID2 expression and overexpression of ID1 promote colon and breast cancer." (PMID 35775482, 2022). "Conversely, ectopic expression of Id2 in MDA-MB-231 and MDA-MB-436 human breast cancer cells did not significantly affect cell growth but markedly reduced the cells' invasive capacity." (PMID 19257909, 2009).